SKP2 (S-phase kinase associated protein 2)
Diseases named in the same sentence as SKP2 in open-access papers (continued):
Sharing a sentence is not in itself a finding about the gene and the disease.
cancer (continued). "MMP14, MDM2, ERBB2, SKP2 and PTGS2, which were previously identified as OGs in human cancer, also have higher rate of amplification in mutation data." (PMID 31205821, 2019). "Consistently, an Skp2 inhibitor, SZL-P1-41, has been shown to restrict cancer stem cell traits and cancer progression." (PMID 30847385, 2019). "We present evidence that AMPK-mediated Skp2 S256 phosphorylation and subsequent Akt activation are critical for VEGF induction and secretion in cancer cells upon metabolic stress." (PMID 30413706, 2018). "Secondly, FOXP3 represses several key target genes in cancer development, such as BRCA1, CD44, HER2/ERBB2, and SKP2, providing a strong link between FOXP3 and DNA repair system, as well as FOXP3 and cell cycle regulation." (PMID 30011797, 2018). "Hundreds of FOXP3 target genes have been identified in both Treg cells and cancer cells so far, including HER2/ERBB2, SKP2, CD44, BRCA1, p21, and LATS2." (PMID 30011797, 2018). "Subsequent studies showed that SKP2 participates in the regulation of subsets of MYC target genes of importance for proliferation and cancer development." (PMID 28665315, 2017). "What possibilities are there to target the MYC/CDK2/SKP2/p27 axis in cancer, i.e., reducing the activity of MYC, CDK2 or SKP2, or boosting nuclear p27 expression?" (PMID 28665315, 2017). "Identification of SKP2 as a novel substrate of FBXW2 extended the list of FBXW2 substrates and revealed its biological function in human cancer." (PMID 28090088, 2017). "Therefore, inactivation of Skp2 could be helpful for the treatment of human cancers." (PMID 27582552, 2016). "Of the top 207 transcripts annotated as ‘cell cycle’ by GO analysis, we focused on nine well-known cell cycle regulators (CCNA2, CCND1, CDK6, CHK1, CHK2, MAPK1, MAP2K1,SKP2, and TFDP1) for further analyses, due to their known functions in cancers." (PMID 26958940, 2016). "Based on the genomic expression data in the whole cancer population, the top prognostic genes were identified, such as FOXM1, CBX7, CREBL2 and SKP2, which were consistent with previous studies." (PMID 27322207, 2016). "Skp2, a critical component of the Skp2-SCF complex E3 ligase, is found highly expressed in numerous cancers including PCa." (PMID 27303918, 2016). "Skp2, as a part of the SCF-Skp2 E3 ubiquitination complex, is required for the removal of several key proteins as Myc, FOXO1, cancer-derived Smad 4 mutants, ISG15 isopeptidase UBP43, and other proteins." (PMID 26682002, 2016). "Both SKP2 elevation and aberrant histone modifications are frequently detected in CRPC and recognized as important markers for cancers." (PMID 25596733, 2015). "To understand the correlation between SKP2 and H3K4me3 as well as the relevance in human PCa, we performed IHC staining of SKP2 and H3K4me3 in human prostate tissue microarrays (TMA) consisting of cancer and normal cases." (PMID 25596733, 2015). "In addition, we found both Skp2 and p27Kip1 to be accurate predictors of disease-free and overall survival, which suggests that these proteins may also be useful markers in locally advanced cancer." (PMID 18644126, 2008). "On the other hand, SKP2 helps C‐MYC retain its TFA in PDCD11‐overexpressed cancer cells, which is not weakened by hindered interaction with SKP2." (PMID 40051297, 2025). "While there are no SKP2 inhibitors currently under clinical trials, preclinical assessment of SKP2 inhibitors using in vitro and in vivo cancer models supports their potential for therapeutic reactivation of p27 and induction of cell-cycle arrest in cancers." (PMID 40002221, 2025). "Notably, the SKP2 and its substrate BRCA2 emerged as a critical regulatory axis with implications for cancer progression and metastasis." (PMID 39062881, 2024). "This allows for us to formulate a hypothesis that in LSCC, SKP2 induces BRCA2 degradation through excessive ubiquitination, leading to further proliferation of tumor cells and facilitating cancer metastasis." (PMID 39062881, 2024).
cancer (continued). "However, FN-RMS cell lines are specifically sensitive to SKP2 knockout in a CRISPR/Cas9 survival screen compared to FP-RMS cells and other cancer cell lines." (PMID 38102140, 2023). "Due to limited specimens, SKP2 mRNA expression differences in various cancers were not verified at the protein level, and there was an imbalance in sample size between the experimental and control groups in the TARGET-AML dataset." (PMID 37308972, 2023). "The residue K242 is also ubiquitinated by the E3 ubiquitin ligases TRAF6 and/or SKP2, suggesting that KDM5B protein levels may be differentially regulated by synchronization of the ubiquitination and sumoylation machinery in cancers." (PMID 36697763, 2023). "Given that the impact of p27 can be disrupted in human cancers by excess proteolysis, C-terminal phosphorylation, or reduced translation, we found that deletion of MESP2 leading to p27 downregulation was due to SKP2-mediated ubiquitination through the proteasome pathway." (PMID 36854722, 2023). "A few studies have reported the potential of SKP2 as a prognostic marker, but its identification effect on cancer status has not been investigated." (PMID 37308972, 2023). "Interestingly, SKP2 is one of transcriptional targets of YAP and sensitizes cancer cells to erastin-induced ferroptosis." (PMID 36147464, 2022). "Further, we assessed the correlation between SKP2 and MKI67 in pan-cancer." (PMID 35685435, 2022). "Many inhibitors of RING finger E3 ligases have demonstrated considerable therapeutic potential in preclinical models and clinical trials of cancer immunotherapy or combination therapy, among which the most studied inhibitors include the IAP family, MDM2, pVHL, Skp2, and β-TrCP." (PMID 34943817, 2021). "In human cancer cells, FOXM1 binds to the promoters of SKP2 and CKS1 and activates them." (PMID 34680943, 2021). "Stable depletion of SKP2, CUL1, or CDK2 rescued sensitivity to Wee1 inhibition in breast and ovarian cancer cell lines, indicating that cancer patients with overexpression of these G1/S regulatory genes could respond robustly to Wee1 inhibitors." (PMID 34671620, 2021). "It is well documented that FOXP3, as a critical master transcription regulator for Treg cell development and function, helps control the activities of various genes (such as oncogenes SKP2 and HER-2/ErbB2) related to the cancer development of the breast and prostate." (PMID 34768829, 2021). "Other cancer amplified genes that also significantly increase ARE reporter activity are MYC (a previously known gene to exert post-transcriptional effect), MYCN, CCND1, CCNE1, SKP2, and NOTCH2." (PMID 34535639, 2021). "To gain novel insight into cancer pathogenesis, we determined the prevalence of genetic and epigenetic alterations in six prototypic SCF complex member genes (SKP1, CUL1, RBX1, SKP2, FBXW7 and FBXO5) from patient datasets extracted from The Cancer Genome Atlas (TCGA)." (PMID 35008511, 2021). "In addition to cell cycle regulation via p21 and p27, SKP2 is known to promote epithelial–mesenchymal transition (EMT), EMT-related stemness properties, and drug resistance in cancer cells by ubiquitinating various substrates." (PMID 32826949, 2020). "In accordance with these recent data, we found in this study that genetic depletion of Fasn resulted in the lower growth rate of c-Myc/MCL1/Cre tumors as well as in the decrease of Cdk1, Cdk2, Skp2, and Survivin/Birc5 genes, which have been previously found to be regulated by FASN in cancer cells." (PMID 33187130, 2020). "Besides, β-TrCP1 promotes another F-box protein FBXW2 ubiquitination, and so does FBXW2 to SKP2, then the β-TrCP1-FBXW2-SKP2 axis presents an oncogene-tumor suppressor-oncogene cascade that controls cancer cell growth." (PMID 32226545, 2020). "Overexpression of SKP2 has been found to correlate with reduced levels of p27KIP1 and is a negative prognostic factor in several human cancers including those of the lung and colon." (PMID 32429232, 2020).
cancer (continued). "The S-phase kinase-interacting protein 2 (SKP2) is an F-box protein acting as a substrate receptor of the SCF complex SCFSKP2, a CRL1 crucially involved in the regulation of cell cycle progression, maintenance of genomic integrity and cancer development." (PMID 32560247, 2020). "In agreement with a possible role for these RNA/DNA hybrid-interacting helicases in cancer, analysis of the COSMIC cancer dataset revealed that these DEAD/H helicases are frequently genetically amplified in cancer, similar to known oncogenes SKP2 and MDM2." (PMID 29742442, 2018). "Remarkably, we found that the AMPK-Skp2-Akt axis is activated in human cancers and that the induction of AMPK-mediated Skp2 S256 phosphorylation significantly predicts poor survival outcome of cancer patients." (PMID 30413706, 2018). "For this reason, it is not surprising that overexpression of SKP2 is observed in diverse type of human cancers." (PMID 30042885, 2018). "We overexpressed Skp2 WT, S256A or S256D mutant into AMPK knockdown cells and found that expressing Skp2 and Skp2 S256D, but not Skp2 S256A, rescued cancer cell survival under hypoxia or glucose deprivation." (PMID 30413706, 2018). "SCF-Skp2 E3 ligase is a target for cancer therapy, but there have been no reports about Skp2 as a target for IPF." (PMID 29415439, 2018). "The Skp2-SCF complex guides target proteins to proteasomal degradation in a cell cycle-dependent manner (from late G1 to early M phase) and its activity appears strongly deregulated in human cancers." (PMID 29614816, 2018). "Overexpression of SKP2 which leads to reduced expression of negative cell cycle regulator CDKN1B is found in cancer cells as a bypass mechanism to escape cell cycle control." (PMID 28466007, 2017). "Skp2 is frequently overexpressed in many human cancers and plays a key role in tumorigenesis, whereas inhibition of Skp2 functions (either proteolytic function or non-proteolytic function) is emerging as a promising and novel anti-cancer strategy." (PMID 27835873, 2017). "Nevertheless, SKP2, an FZR1 target, is up-regulated in many cancers." (PMID 27402801, 2016). "Since these chemical inhibitors exhibit side effects, it is important to discover natural agents with non-toxic nature to inactivate Skp2 in human cancer." (PMID 27582552, 2016). "Finally, in recent years, SKP2 overexpression has been shown to mediate resistance to TRAIL induced apoptosis, and radio- and chemoresistance of human cancer cells." (PMID 23226679, 2012). "We further demonstrate that the SIRT3 tumor suppressor interacts with and deacetylates Skp2, suggesting that targeting Skp2 or the p300/SIRT3 axis could be a novel approach for the treatment of human cancers, especially those with up-regulation of Skp2." (PMID 23230084, 2012). "For example, it was discovered that Skp2 regulates the rate of degradation of the Cdk inhibitor p21 and of the forkhead transcription factor FOXO-1, two other cell cycle regulatory proteins that play important roles in cancer progression." (PMID 16859513, 2006). "The exact mechanisms that promote Skp2 overexpression in these cancers are at present not well understood." (PMID 16859513, 2006). "This suggests that targeting RCC1 might have potential in combinatory therapy with first-line anti-cancer drugs like EGFR inhibitors, mTOR inhibitors and AR inhibitors, whose effectiveness are often compromised by increased cytoplasmic distribution of Skp2." (PMID 38561375, 2024). "Moreover, the potential clinical significance of SKP2 (e.g., distinguishing tumor patients from individuals without cancer) and the immune correlation of the gene in a variety of tumors are unclear." (PMID 37308972, 2023).
cancer (continued). "In our study, the expression level of SKP2 was significantly positively correlated with the expression levels of three DNMTs and five MMRGs, suggesting that the effect of SKP2 on DNMT and MMR may be one of the critical pathways for the gene to promote cancer." (PMID 37308972, 2023). "Hence, SKP2, instead of CDC20, positively correlates with YAP1 expression in pan-cancer." (PMID 35685435, 2022). "Specifically, considering the current situation that there were no clinically viable drugs that directly target YAP in cancer, MLN4924, as a drug that could inhibit the activity of Skp2, might be a potential treatment agent for attenuating the proliferation of tumor cells in YAP-driven cancers." (PMID 35685435, 2022). "Apart from targeting Skp2, development of specific inhibitors targeting Akt upstream regulators, such as TRAF6, SETDB1 and JMJD2A, may also serve as a novel and innovative strategy for eradicating hyperactive Akt-driven human cancers." (PMID 36180910, 2022). "In parallel, YAP underwent K63-linked polyubiquitination by SCF S-phase kinase-associated protein 2 (SKP2) E3 ubiquitin ligase, a Hippo-independent, nonproteolytic ubiquitination that enhances YAP nuclear trafficking and transcriptional activity in cancer cells." (PMID 36326820, 2022). "In cancer, the 14-3-3ζ is substantially upregulated in various carcinomas, where it has been proposed to enhance cancer cell survival through binding of the p85 subunit of the PI3K resulting in activation of AKTs and/or by impairing tumor cell senescence in a STAT3/SKP2/p27-dependent manner." (PMID 33829040, 2021). "There are not currently Skp2-Cks1 inhibitors for the treatment of malignant tumors in clinic." (PMID 34702937, 2021). "Interestingly, RBX1 and SKP2 tend to be hypomethylated across all cancer types, irrespective of copy number status, whereas FBXW7 is differentially methylated across cancer types." (PMID 35008511, 2021). "However, there are no reports to date claiming that Skp2 overexpression alone is sufficient to transform primary culture cells into malignant tumors." (PMID 32313103, 2020). "This newly identified AMPK/Skp2/Akt pathway provides not only the molecular basis of how AMPK serves a protective and survival advantage under diverse stresses, but also offers a novel therapeutic strategy for cancer treatment and overcoming acquired resistance to EGFR targeted therapy." (PMID 30413706, 2018). "HUVEC cells cultured with conditioned medium from AMPK knockdown cancer cells displayed lower tube and branch numbers, which could be partially rescued by Skp2 S256D, but not by Skp2 S256A." (PMID 30413706, 2018). "Using constitutively active Skp2, reduced DAB2IP protein was detected in 293 wild-type (wt) cells, Taken together, Skp2-mediated UPS plays an important role in regulating DAB2IP protein expression post-translationally in both immortalized normal prostate epithelial and cancer cells." (PMID 25115390, 2014). "The top-ranked genes by NGP-PLK1, MCM2, MCM3, MCM7, MCM10 and SKP2 might coordinate to promote cell cycle related processes in cancer but not normal cells." (PMID 22838965, 2012). "Our results suggest that the top-ranked genes by NGP-PLK1, MCM2, MCM3, MCM7, MCM10 and SKP2 might coordinate to promote cell cycle related processes in cancer but not normal cells." (PMID 22838965, 2012). "In the absence of activated Akt1, whether and how cytoplasmic Skp2 is involved in the development of metastasis and cancer progression remains to be elucidated." (PMID 23300741, 2012). "With above results, it is suspected that PLK1, MCM complex, SKP2 and some of their interacting genes may play important roles to promote cell cycle related processes in cancer but not normal cells." (PMID 22838965, 2012). "Recent studies have also found that Skp2 may modulate invasion of cancer cells independent of p27 degradation." (PMID 18922157, 2008).
cancer (continued). "We found that MCF7CCNE1amplified cells were more sensitive to SKP2 inhibition when compared to parental MCF7 cells, corroborating the hypothesis that RBness cancers harbor synthetic lethal targeting opportunities similar to those found in RB1-defective cancers." (PMID 40138429, 2025). "In addition, no body-fluid samples were collected to detect SKP2 screening for pan-cancer." (PMID 37308972, 2023). "As a hot research spot for therapeutic target-drugs of cancers, inhibition of Skp2 by genetic deletion or pharmacological blockade showed little effect on normal tissues based on murine models, indicating that Skp2 inhibition may not induce serious adverse effect." (PMID 37089937, 2023). "However, there are no reports focusing on SKP2 in pan-cancer." (PMID 37308972, 2023). "In agreement with outcomes of previous research, it was confirmed that by synergisticly arresting cancer cells at G0-G1 and G2-M phases, the combined treatment regimen of Vem and VERU-111 could overcome the Vem-resistance through enhanced apoptosis and compromised Skp2-AKT signaling pathway." (PMID 33841154, 2021). "Moreover, the critical role of Skp2 phosphorylation in cancer cell has not yet been explored." (PMID 28446188, 2017). "In our results, calycosin affected two check points gene transcription; for example TFDP-1 and SKP2 were markedly downregulated and CDC2 and CCNB1 were upregulated expression and downregulated expression of CDKN2D which may block the G1/S and G2/M transition in cancer cells." (PMID 24455688, 2013). "For patients with this cancer at AJCC stage I, males were observed to have lower SKP2 expression than females; this discrepancy was not identified for KIRP at stages II, III, or IV." (PMID 37308972, 2023). "While EGF-induced cancer cell migration was reduced upon AMPK knockdown, restoration of Myr-Akt or Skp2 S256D, but not Skp2 S256A, in AMPK knockdown cancer cells rescued such defect (k and Supplementary 6l)." (PMID 30413706, 2018). "Moreover, overexpression of Skp2 S256D, but not Skp2 S256A, also rescued Glut1 transcription, glucose uptake, and lactate production in AMPK knockdown cancer cells." (PMID 30413706, 2018). "However, up to now, there is almost no research regarding the relationship between SKP2 and RIBE in human cancers." (PMID 28178195, 2017).